TPT1 (tumor protein, translationally-controlled 1)
Diseases named in the same sentence as TPT1 in open-access papers (continued):
Sharing a sentence is not in itself a finding about the gene and the disease.
cancer (82 papers, 2010 to 2025). A tumor composed of atypical neoplastic, often pleomorphic cells that invade other tissues. "CKS2 and TPT1 have both been implicated in cancer, including as potential therapeutic targets." (PMID 40809150, 2024). "Recently, inhibition of TPT1 to attain tumor reversion has provided a new approach for cancer therapy." (PMID 34589516, 2021). "TPT1 is frequently elevated in cancers, leading to suppression of apoptosis, promotion of metastasis, and resistance to anticancer therapy." (PMID 34589516, 2021). "Remarkably, overexpression of HSP27, TPT1, and PRXD6 proteins has been also associated to apoptosis inhibition and resistance of cancer cells to chemotherapeutic drugs." (PMID 23724044, 2013). "The release of tumor protein, translationally-controlled 1 (TPT1) by dying cancer cells has been shown to facilitate the recruitment of myeloid-derived suppressor cells (MDSCs) to the tumor microenvironment (TME), thereby promoting local immunosuppression and disease progression." (PMID 39555062, 2024). "In recent years, researches based on Tpt1 gene mainly focused on cancer cells." (PMID 38025678, 2023). "Furthermore, elevated TPT1 expression was significantly correlated with lymph node metastasis and a low differentiation degree of the cancer." (PMID 34589516, 2021). "Inhibition of TPT1 by anti-sense cDNA or siRNA in vitro or injection of antagonistic drugs, such as anti-histaminic compounds into tumor-bearing mice, suppressed the malignant phenotype of cancers of the breast, lung, and colon and melanoma." (PMID 34589516, 2021). "Bearing in mind that TPT1 might execute different functions in the context of benign cervical inflammation, its steady increase through cancer development suggests that TPT1 is an important signature manifesting itself long before cancer diagnosis." (PMID 34589516, 2021). "The finding that high expression of TPT1 significantly correlated with both lymph node metastasis and cancer cell differentiation implies that it may promote cancer progression." (PMID 34589516, 2021). "TCTP (gene symbol: TPT1), also referred to as histamine-releasing factor (HRF) or fortilin, is a highly-conserved, multifunctional protein, which has been implicated in a range of cell biological, as well as disease processes, in particular cancer." (PMID 28143584, 2017). "Here, we found that the levels of TPT1 within the tumor significantly correlated with the response to anti-PD-L1 therapy and survival in cancer patients, indicating that the expression status of TPT1 may serve as a marker to predict the clinical outcomes of anti-PD-L1 therapy." (PMID 35440620, 2022). "Moreover, TPT1 was verified as a crucial factor in cancer reversion." (PMID 33428595, 2021). "Cancer-associated factor Tpt1 has been reported to activate the transcription of Oct4 and Nanog in transplanted somatic nuclei in Xenopus oocytes, but knockdown of Tpt1 by small interfering RNA (siRNA) does not reduce Oct4 expression in mouse embryos." (PMID 28102431, 2017). "We also found that the serum TPT1 concentrations had a tendency to increase in CINIII and cancer patients and was significantly higher in cancer patients than in the healthy population." (PMID 34589516, 2021). "Cancer-related transcripts of AKR1C2, TPT1 and RPS27A were also down-regulated by AZD3355 in phHSCs." (PMID 34675338, 2021). "TPT1/TCTP (tumor protein, translationally-controlled 1) is a conserved onco-protein that is overexpressed in several human cancers, and participates in multiple cellular activities including protein synthesis, cell survival and malignant transformation." (PMID 32792860, 2020).
cancer (continued). "After exposure to VPA, we observed changes in the expression levels of several genes (TPT1, ARAP3, and KLHDC8B) that are reported to be important in cancer-related pathways." (PMID 26379622, 2015). "The result demonstrated that a high TPT1 protein level significantly correlated with lymph node metastasis (p = 0.019) and a low degree of tumor differentiation (p = 0.035), implying its link with EMT and cancer aggressiveness." (PMID 34589516, 2021). "More specifically, therapeutic modulation of FN1, TPT1, RTN4, and FSTL1, for which knockdown has been shown to result in reduced cell proliferation and migration in cancer cells, may represent new potential therapeutic avenues for pterygia as well." (PMID 35174178, 2021). "Tpt1, tumor protein translationally-controlled 1, also known as p23, fortilin, or histamine releasing factor (HRF), plays a role in carcinogenesis, is up-regulated in some cancer cells, and promotes colorectal cancer invasion and metastasis." (PMID 32842712, 2020). "Moreover, depletion of TPT1 in HeLa cells or mice not only promoted apoptosis by BCL2 inhibition but enhanced the overall autophagy flux, two attractive strategies against cancer." (PMID 34589516, 2021). "Although not known to be as structured as TPT1, LCP1 (lymphocyte cytosolic protein 1) is also over-expressed in many different cancers and may be involved in cell mobility." (PMID 29317542, 2018).
tumor (82 papers, 2006 to 2025). "TPT1/TCTP is a switch regulating tumor reversion and loss of TPT1 results in loss of malignancy of tumor." (PMID 37033948, 2023). "The TPT1/TCTP gene is a tumour protein that controls translation and encodes highly structured mRNA shielded by ribosomal protein, which is very similar to virus particles, activating protein kinase R." (PMID 35493728, 2022). "Specifically, SNORA31 was significantly down-regulated in association with its host gene TPT1, which encodes for a critical protein involved in the control of stemness, pluripotency, or tumor reversion." (PMID 24004562, 2013). "To directly link TCTP to the ICB-refractory phenotypes of CT26 P3 tumor cells, we silenced TPT1 in CT26 P3 cells using siRNAs." (PMID 35440620, 2022). "Among 15 genes in the signature, except four genes, RAB27A, ADGRB1, MT1F, and TPT1, the remaining were differentially expressed between tumor and normal tissues." (PMID 33329725, 2020). "TPT1 protein has been involved in many biological processes including cell growth, tumor reversion, and induction of pluripotent stem cells." (PMID 23724044, 2013). "Both upregulation of TGF-β pathway and TPT1 are known factors that suppress anti-tumor immunity." (PMID 37033948, 2023). "Additionally, overregulation of miR-216b targets the translationally controlled 1(TPT1) tumor proteins, leading to tumor growth suppression." (PMID 36292753, 2022). "For CXCL1 and TPT1, this tumor proliferative effect is already known." (PMID 19558675, 2009). "The TECs0 cluster was characterized by TPT1 and VWF expression and was involved in endothelial cell differentiation and angiogenesis regulation, promoting tumor expansion by ensuring an oxygen and nutrient supply." (PMID 40123905, 2025). "Except for activating TGF-β, another observed dominant character of subgroup 2 is the upregulation of TPT1. the high metastatic potential of CRC can be induced when TGF-β activation is mixed in tumor cells that still maintain some epithelial characters." (PMID 37033948, 2023). "A tendency towards the upregulation of several known suppressors of anti-tumor immunity and initiators of epithelial-mesenchymal transition (EMT) was observed: TGFBR1, TGFBR2, TGFB3 and TPT1." (PMID 37033948, 2023). "In the top 10 altered couples for these tumor types, 9 are identical: SNORA13/EBP41L4A-AS1, SNORA27/RPL21, SNORA31/TPT1, SNORA71E/SNHG11, SNORA72/RPL30, SNORD102/RPL21, SNORD12/ZFAS1, SNORD12B/ZFAS1, and SNORD12C/ZFAS1." (PMID 32046192, 2020). "Expressed genes found in both the tumor group and the NPC with antitumor effect were Camk2, CD81, Kai1, TPT1 and AXL." (PMID 19558675, 2009). "When antibodies specific for CXCL1, TPT1 or CD81 were added to tumor co-cultures with NPC, the suppressive effect by the NPC was significantly enhanced in several combinations of NPC and tumor, although to a varying extent." (PMID 19558675, 2009). "In addition to chaperones, which were shown to play a significant role for the induction of anti-tumor immune responses, we identified a number of TAAs interacting with NS1 (i.e., TPT1, NUMA1, SPRYD4, SND1, and GNL3)." (PMID 36680249, 2023). "While there was no alteration in the percentage of apoptotic tumor cells in siTPT-treated and siGFP-treated P3 tumor cells without CTLs, TPT1 knockdown sensitizes tumor cells to CTL-mediated apoptosis." (PMID 35440620, 2022).
tumor (continued). "The fact that addition of an antibody enhances the suppressive effect of HiB5 and ST14A on tumor growth gives hints that the suppressive effect of these NPC is not due to their secretion of TPT1, CD81 and CXCL1, Gas6/Axl but to other factors." (PMID 19558675, 2009). "Addition of antibodies against CXCL1, CD81, and TPT1 had various effects either inhibiting the tumor proliferation or showing no significant changes upon the tumors." (PMID 19558675, 2009).
infection (10 papers, 2011 to 2025). The state of being infected such as from the introduction of a foreign agent such as serum, vaccine, antigenic substance or organism. "Additionally, our analyses of human and mouse gastric tissues confirmed elevated expression levels, and a positive correlation among TPT1, OCT1, and CDX2 in GIM which are associated with H. pylori SlyD infection." (PMID 39915880, 2025). "The correlation among hnRNPK/TPT1/OCT1, GIM, and H. pylori SlyD infection was further validated in human and Mongolian gerbils (MGs) gastric tissues." (PMID 39915880, 2025). "Additionally, IHC staining of human and MGs gastric tissues revealed a correlation between hnRNPK, TPT1, GIM, and H. pylori SlyD infection." (PMID 39915880, 2025).
TPT1 also shares sentences with these, for which no sentence is quoted: Allergy (11 papers); hepatocellular carcinoma (5); Hypertension (5); malaria (5); Alzheimer disease (4); asthma (4); diabetes (3); food allergy (3); heart failure (3); atopic dermatitis (2); cataract (2); cerebral malaria (2); Down syndrome (2); gallbladder cancer (2); gastric cancer (2); immune diseases (2); leukemia (2); rheumatoid arthritis (2); tuberous sclerosis (2); virus infection (2); acute lymphoblastic leukemia (1); acute myelogenous leukemia (1); adenovirus infection (1); allergic rhinitis (1); Arrhythmia (1); atherosclerosis (1); bacterial infection (1); benign prostatic hyperplasia (1); benign tumors (1); breast hyperplasia (1).
A further 51 diseases each share a sentence with TPT1 in 1 paper.